SFMBT2 (Scm like with four mbt domains 2)
Description:
Transcriptional repressor of HOXB13 gene.
Synonyms: KIAA1617
Tractability: PROTAC: ubiquitination databases record sites on it.
Gene: Protein-coding gene on chromosome 10 (7,158,624 to 7,411,488, reverse strand). Ensembl gene ENSG00000198879.
Subcellular location: Nucleus
Subcellular location (Human Protein Atlas): Nuclear speckles; Nucleoplasm
Gene Ontology:
Molecular function: histone binding; protein binding; chromatin binding; transcription corepressor activity
Biological process: negative regulation of gene expression; negative regulation of DNA-templated transcription; regulation of DNA-templated transcription
Cellular component: nuclear speck; nucleoplasm; nucleus
Genetic constraint (gnomAD): Loss-of-function variants: 30 observed, 93.2 expected, observed/expected ratio (o/e) 0.32, 90% interval 0.24 to 0.44. The upper end of that interval is the gene's LOEUF score, 0.44, which puts it in group 1 of 6, group 1 being the genes least tolerant of losing a copy. Missense variants: 873 observed, 998.76 expected, observed/expected ratio (o/e) 0.87, 90% interval 0.83 to 0.92. Synonymous variants: 372 observed, 389.54 expected, observed/expected ratio (o/e) 0.95, 90% interval 0.88 to 1.04.
Homologues: Orthologues: chimpanzee SFMBT2 (99% identical), macaque SFMBT2 (98% identical), rabbit SFMBT2 (95% identical), dog SFMBT2 (92% identical), pig SFMBT2 (90% identical), mouse Sfmbt2 (76% identical), rat Sfmbt2 (75% identical), tropical clawed frog sfmbt2 (75% identical), zebrafish sfmbt2 (60% identical), Drosophila melanogaster l(3)mbt (14% identical), Drosophila melanogaster Sfmbt (12% identical), Caenorhabditis elegans lin-61 (9% identical), and 1 more. Paralogues in human: SFMBT1 (53% identical), SCML2 (20% identical), SCMH1 (19% identical), L3MBTL3 (14% identical), L3MBTL1 (13% identical), L3MBTL4 (13% identical), L3MBTL2 (13% identical), PHC1 (12% identical), MBTD1 (12% identical), PHC2 (11% identical), SCML4 (11% identical), PHC3 (11% identical), and 6 more.
Diseases named in the same sentence as SFMBT2 in open-access papers:
SFMBT2 is named in the same sentence as 24 diseases in open-access papers, as found by Europe PMC text mining. Sharing a sentence is not in itself a finding about the gene and the disease. The quoted sentences say what the papers report.
gastric cancer (6 papers, 2017 to 2024). A primary or metastatic malignant neoplasm involving the stomach. "In gastric cancer, miR-182-5p has been reported to be sponged by circ-SFMBT2 to regulate the expression of CREB1 mRNA." (PMID 38877514, 2024). "Circ-SFMBT2 contributes to the development and tumorigenesis of gastric cancer via regulation of the miR-1276/CTNNB1/Wnt/β-catenin axis." (PMID 35513849, 2022). "Some Wnt pathway-related circRNAs (circ0005654, circ-SFMBT2, circ_SMAD4, circRNA_0044516, and circHIPK3) are markedly upregulated in gastric cancer." (PMID 35513849, 2022). "Circ-SFMBT2 upregulation indicates higher levels of oxidative stress in gastric cancer." (PMID 35513849, 2022). "Additionally, circ0005654, circRNA_ASAP2, circ-SFMBT2, and circHIPK3 obviously promote gastric cancer cell migration and invasion." (PMID 35513849, 2022). "Similarly, highly expressed circ-SFMBT2 was observed in gastric cancer tissues and proved to participate in the pathogenesis of gastric cancer via miR-182-5p sponging." (PMID 34271965, 2021). "Apart from these down-regulated circRNAs, a circRNA named circ-SFMBT2 revealed an increased expression level in gastric cancer plasma samples compared with healthy people, suggesting it could be applied to detect gastric cancer." (PMID 33816529, 2021). "Most of the highest expressed circRNA genes in gastric cancer samples are also present in tumor-adjacent tissue (CFLAR, CORO1C, HIPK3, ASXL1 and SFMBT2)." (PMID 29109417, 2017).
prostate carcinoma (4 papers, 2016 to 2024). A carcinoma that arises from epithelial cells of the prostate gland. "In this study, we found that expression level of SFMBT2 is altered during prostate cancer progression and has been associated with the migration and invasion of prostate cancer cells." (PMID 27340776, 2016). "Given that infiltration of adipocytes or macrophages into the tumor microenvironment contributes to prostate cancer progression, we further investigated whether SFMBT2 regulates the expression of chemokines, which are linked to cell infiltration." (PMID 32971847, 2020). "Here we investigated whether the down-regulation of SFMBT2 regulates the infiltration of preadipocytes and tumor-associated macrophages (TAMs) in prostate cancer." (PMID 32971847, 2020). "Expression of SFMBT2 in prostate cancer was strongly associated with clinicopathological features." (PMID 27340776, 2016). "SFMBT2 was demonstrated to suppress metastasis of prostate cancer cells, and SFMBT2-silenced tumor cells enhanced M2 polarization of macrophages in microenvironment." (PMID 38734627, 2024). "Their expression was also increased in prostate cancers expressing a low level of SFMBT2, which are the more invasive cancers." (PMID 32971847, 2020). "We previously demonstrated that down-regulation of mammalian PcG protein SFMBT2 promotes prostate cancer metastasis through the up-regulation of MMPs." (PMID 32971847, 2020). "In conclusion, our study provides evidence that the down-regulation of SFMBT2 promotes prostate cancer metastasis by the recruitment of preadipocytes and TAMs through NF-κB-dependent up-regulation of chemokine expression." (PMID 32971847, 2020). "We also found that the up-regulation of CXCL8, CCL2, CXCL10, and CCL20 expression is dependent on NF-κB activation in prostate cancer cells expressing a low level of SFMBT2." (PMID 32971847, 2020). "We previously reported that down-regulation of SFMBT2 promotes prostate cancer metastasis through the up-regulation of MMPs and that expression level of SFMBT2 inversely correlates with the prognosis of prostate cancer patients such as invasion and metastasis." (PMID 32971847, 2020). "We previously reported that SFMBT2 acts as a transcriptional repressor for MMPs in prostate cancer cells." (PMID 32971847, 2020). "We previously reported that SFMBT2 (Scm-like with four mbt domains 2) regulates the expression of matrix metalloproteinases (MMPs) and migration and invasion of cancer cells in prostate cancer." (PMID 32971847, 2020). "We found increased infiltration of Pref-1 and CD29 positive preadipocytes in prostate cancer tissues induced by intraprostatic injection of LNCaP cells stably transfected with SFMBT2 shRNA and in tissues of prostate cancer patients." (PMID 32971847, 2020). "The aim of the current study is to evaluate the role of SFMBT2 in regulating cell penetration into the prostate cancer microenvironment." (PMID 32971847, 2020). "Our analysis indicated the high expression of CXCL8, CCL2, CXCL10, and CCL20 in prostate cancer tissues expressing a low expression level of SFMBT2, which is correlated with high Gleason scores." (PMID 32971847, 2020). "Expression of CXCL8, CCL2, CXCL10, and CCL20 was also elevated in prostate cancer patients having a higher Gleason score (≥8), which had substantially lower SFMBT2 expression." (PMID 32971847, 2020). "In this study, we suggest that chemokines produced from prostate cancer cells expressing a low level of SFMBT2 promote the infiltration of preadipocytes and TAMs." (PMID 32971847, 2020). "Immunohistochemical analysis indicated increased numbers of Pref-1 and CD29 positive cells in prostate cancer induced by intraprostatic injection of LNCaP cells stably transfected with SFMBT2 shRNA." (PMID 32971847, 2020). "Expression of CXCL8, CCL2, CXCL10, and CCL20 is dependent on NF-κB activation in prostate cancer cells expressing low levels of SFMBT2." (PMID 32971847, 2020).
prostate carcinoma (continued). "Further investigation is needed to explore the exact role of chemokines induced by down-regulation of SFMBT2 in prostate cancer progression." (PMID 32971847, 2020). "Metastatic tumors of LNCaP cells expressing shSFMBT2-GFP was observed in the gonad and kidney, indicating that knockdown of SFMBT2 promotes prostate cancer metastasis." (PMID 27340776, 2016). "The clinical relevance of SFMBT2 was examined by immunohistochemistry using commercially available prostate cancer tissue arrays." (PMID 27340776, 2016). "We showed that the expression level of SFMBT2 is critical for cell migration and invasion, which are fundamental features of prostate cancer malignancy through direct or indirect regulation of MMP-2, MMP-3, MMP-9, MMP-26, N-CoR, and KAI1 gene expression." (PMID 27340776, 2016). "To further evaluate a possible role of SFMBT2 in prostate cancer progression, we first analyzed expression level of SFMBT2 in various prostate cancer cells lines." (PMID 27340776, 2016). "The expression level of SFMBT2 is high in poorly metastatic prostate cancer cells compared to highly metastatic prostate cancer cells." (PMID 27340776, 2016). "We found previously that mammalian SFMBT2, a polycomb gene (PcG), regulates cell growth in prostate cancer cells." (PMID 27340776, 2016). "In contrast, SFMBT2 expression of prostate cancer patient's specimens was low in 60.4 % (32/53 cases), moderate in 32.1% (17/53 cases), and high in 7.5% (4/53 cases)." (PMID 27340776, 2016). "Knockdown of SFMBT2 increases prostate cancer cell migration and invasion via direct repression of target genes such as MMP-9, MMP-26, and N-CoR in LNCaP and VCaP cells." (PMID 27340776, 2016). "In conclusion, our study provides evidence that SFMBT2 regulates prostate cancer metastasis either by direct repression of YY1 target genes such as MMP-9, MMP-26, and N-CoR and by indirect regulation of MMP-2, MMP-3, and KAI1 gene expression." (PMID 27340776, 2016). "The mammalian PcG protein SFMBT2 has been shown to play an important role in prostate cancer cell growth through HOXB13 gene regulation via interaction with YY1." (PMID 27340776, 2016). "SFMBT2 was previously reported to inhibit the infiltration of preadipocytes in prostate cancer, suggesting that the function of SFMBT2 may be associated with the lipid metabolism." (PMID 38734627, 2024). "However, another paper showed opposite results, in which SFMBT2 promoted viability of prostate cancer cell line DU145." (PMID 38734627, 2024). "In addition, IL-6 expression was proportionally related to a high Gleason score of ≥8 and increased in prostate cancers expressing a low level of SFMBT2." (PMID 32971847, 2020). "We next investigated whether SFMBT2 regulates the infiltration of adipocytes and TAMs by up-regulation of chemokine expression in prostate cancer." (PMID 32971847, 2020). "In this study, we investigated whether SFMBT2 regulates cell infiltration into the prostate cancer microenvironment." (PMID 32971847, 2020). "Moreover, increased IL-6 from infiltrated preadipocytes and TAMs promoted migration and invasion of prostate cancer cells expressing a low level of SFMBT2." (PMID 32971847, 2020). "In addition, IL-6 from infiltrated preadipocytes and TAMs further promotes migration and invasion of prostate cancer cells expressing a low level of SFMBT2." (PMID 32971847, 2020). "The expression level of SFMBT2 is low in highly metastatic prostate cancer cells." (PMID 32971847, 2020). "Taken together, our results suggest that down-regulation of SFMBT2, which is correlated with a high Gleason score (≥8), promotes the infiltration of preadipocytes and TAMs through the up-regulation of chemokine expression in prostate cancer cells." (PMID 32971847, 2020). "We also tested whether culture media from PC3 cells, highly metastatic prostate cancer cells endogenously expressing a low level of SFMBT2, have a similar effect on the migration of 3T3-L1 preadipocytes and TAMs." (PMID 32971847, 2020).
prostate carcinoma (continued). "Prostate cancer patients with higher Gleason scores (≥8) have substantially lower SFMBT2 expression than patients with lower Gleason scores, indicating that SFMBT2 may have an anti-metastatic function." (PMID 32971847, 2020). "Recently, SFMBT2, another PcG protein, was shown to be involved in prostate cancer cell growth." (PMID 27340776, 2016). "In this study, we further characterized the function of SFMBT2 in prostate cancer metastasis." (PMID 27340776, 2016). "The tail vein or intraprostatic injection of SFMBT2 knockdown LNCaP cells in mice significantly induces metastasis, indicating that SFMBT2 may inhibit metastasis of prostate cancer in vivo." (PMID 27340776, 2016). "Moreover, we found that tail vein or intraprostatic injection of SFMBT2 knockdown LNCaP cells significantly induces metastasis, indicating that SFMBT2 acts as a metastasis suppressor in prostate cancer in vivo." (PMID 27340776, 2016). "Overall, low expression of SFMBT2 appears to be related to prostate cancer." (PMID 27340776, 2016). "Interestingly, expression level of SFMBT2 inversely correlates with Gleason score in prostate cancer patients." (PMID 27340776, 2016). "In this study, we investigated the role of SFMBT2 in metastasis of prostate cancer." (PMID 27340776, 2016). "Taken together, our findings suggest that regulation of SFMBT2 may provide a new therapeutic strategy to control prostate cancer metastasis as well as being a potential biomarker of metastatic prostate cancer." (PMID 27340776, 2016). "In addition, expression level of SFMBT2 in prostate cancer patients is negatively correlated with a high Gleason score (≥ 8), which seems closely related to prostate cancer invasion and metastasis." (PMID 27340776, 2016). "SFMBT2 could be used as a novel biomarker and target for prostate cancer treatment." (PMID 32971847, 2020). "Thus, the regulation of SFMBT2 may provide a new therapeutic strategy to inhibit prostate cancer metastasis, and SFMBT2 could be used as a potential biomarker in prostate cancer metastasis." (PMID 32971847, 2020). "Thus, expression levels of chemokines and SFMBT2 were analyzed in prostate cancer tissues." (PMID 32971847, 2020). "Similarly, we found that SFMBT2 acts as a transcriptional repressor of TNFα gene expression and knockdown of SFMBT2 results in increased expression of TNFα, which activates the NF-κB signaling and plays an important role in prostate cancer progression." (PMID 32971847, 2020). "Although we do not know how SFMBT2 knockdown results in NF-κB activation at present, recent studies have demonstrated that NF-κB activation maybe associated with metastasis of prostate cancer." (PMID 27340776, 2016). "Therefore, regulation of SFMBT2 expression or SFMBT2 activity may provide a new therapeutic strategy to suppress cancer cell migration and invasion as well as a potential biomarker in prostate cancer progression." (PMID 27340776, 2016). "For instance, SFMBT2 assisted in transcription suppression of MMP9 and MMP26, thereby inhibited metastasis of prostate cancer cells." (PMID 38734627, 2024). "We found that the down-regulation of SFMBT2 promotes the up-regulation of CXCL8, CCL2, CXCL10, and CCL20 expression in prostate cancer cells, resulting in elevated infiltration of preadipocytes and TAMs." (PMID 32971847, 2020). "Thus, SFMBT2 could be used as a novel biomarker and target for prostate cancer treatment." (PMID 32971847, 2020). "In addition, HoxB13, which is identified as a target gene of SFMBT2 transcriptional repressor, may contribute to NF-κB-mediated prostate cancer metastasis because over-expression of HoxB13 leads to reduced expression of IκBα and enhanced the nuclear translocation of NF-κB p65 in LNCaP cells." (PMID 32971847, 2020). "We found that the down-regulation of SFMBT2 promotes the infiltration of preadipocytes and TAMs through up-regulation of CXCL8, CCL2, CXCL10, and CCL20 expression in prostate cancer." (PMID 32971847, 2020).
prostate carcinoma (continued). "Recently, we found that Scm-like with four MBT domains protein 2 (SFMBT2), another PcG protein, is involved in prostate cancer metastasis." (PMID 32971847, 2020). "In case of LNCaP, SFMBT2 interacts with YY1 and represses MMP2, MMP3, and MMP9 and inhibits invasion and migration of prostate cancer cells, and illustrating both pro and anti-role of YY1 in prostate cancer growth." (PMID 31824839, 2019). "While, YY1 largely acted as a tumor promoter in prostate cancer, upon interacting with SFMBT2 (Scm-like with four mbt domains 2), YY1 acts both as a tumor promoter and suppressor in prostate cancer." (PMID 31824839, 2019). "SFMBT2 interacts with YY1 and regulates cell growth through repression of the HOXB13 gene in DU145 prostate cancer cells." (PMID 27340776, 2016). "A previous article reported the binding between SFMBT2 and HDAC3 in prostate cancer cells." (PMID 38734627, 2024). "The expression level of SFMBT2 was high in normal RWPE-1 prostate cells and poorly metastatic LNCaP prostate cancer cells, but low in highly metastatic prostate cancer cells, such as PC3 and DU145, indicating that SFMBT2 expression is likely related to metastasis." (PMID 27340776, 2016).
brain tumor (3 papers, 2021 to 2024). "This study was to evaluate the function and mechanism of circRNA Scm-like with four malignant brain tumor domains 2 (circ-SFMBT2) in esophageal cancer (EC)." (PMID 34530825, 2021).
breast cancer (3 papers, 2012 to 2023). A primary or metastatic malignant neoplasm involving the breast. "Regarding circRNA-SFMBT2 knockdown, si2-circRNA-SFMBT2 had a higher silencing efficiency than si1-circRNA-SFMBT2 and did not alter the expression of SFMBT2 in breast cancer cells." (PMID 37524698, 2023).
metastatic prostate carcinoma (2 papers, 2016 to 2020). A carcinoma that arises from the prostate gland and has spread to other anatomic sites. "SFMBT2, an epigenetic factor, is downregulated in metastatic prostate cancer." (PMID 32971847, 2020).
acute myeloid leukemia (1 paper, 2024). Acute myeloid leukemia (AML) is a group of neoplasms arising from precursor cells committed to the myeloid cell-line differentiation. "Studies have shown that SFMBT2 can promote malignant proliferation of acute myeloid leukemia cells by regulating the miR‐582‐3p/ZBTB20 pathway." (PMID 39711442, 2024).
adenoma (1 paper, 2026). A neoplasm arising from the epithelium. "SFMBT2 expression was high in normal intestinal mucosa but progressively reduced in advanced adenoma, primary CRC, and metastatic lesions, accompanied by increased promoter methylation." (PMID 41809030, 2026).
colorectal adenocarcinoma (1 paper, 2023). The most common type of colorectal carcinoma. "Thus, lncRNA LINC02535 was confirmed to induce colorectal adenocarcinoma progression via targeting miR-30d-5p/CHD1 axis, and circ-SFMBT2 sponges miR-30d-5p that directly targets CHD1 and therefore plays an oncogenic role in colorectal adenocarcinoma." (PMID 37175555, 2023).
colorectal cancer (1 paper, 2026). A primary or metastatic malignant neoplasm that affects the colon or rectum. "Here, we investigated the role of SFMBT2 promoter hypermethylation in colorectal cancer (CRC) development and its clinical relevance." (PMID 41809030, 2026).
dementia with Lewy bodies (1 paper, 2024). "SFMBT2 has been reported to have a microglial transcriptional signature, to be differentially expressed in Parkinson’s Disease, and has been suggested to be involved in dementia with Lewy bodies." (PMID 38422004, 2024).
leukemia (1 paper, 2023). A malignant (clonal) hematologic disorder, involving hematopoietic stem cells and characterized by the presence of primitive or atypical myeloid or lymphoid cells in the bone marrow and the blood. "We identified recurrently affected genes by SVs, such as FOCAD/HACD4, MANBA, and SFMBT2 that were validated by long-read sequencing and/or RNA-seq in at least 1 leukemia." (PMID 37469802, 2023).
metastatic tumors (1 paper, 2024). "SFMBT2 overexpression reduced the number and size of metastatic tumors, and SFBMT2 silencing promoted the tumor formation in lung." (PMID 38734627, 2024).